INTS13 (integrator complex subunit 13)
Description:
Component of the integrator complex, a multiprotein complex that terminates RNA polymerase II (Pol II) transcription in the promoter-proximal region of genes. The integrator complex provides a quality checkpoint during transcription elongation by driving premature transcription termination of transcripts that are unfavorably configured for transcriptional elongation: the complex terminates transcription by (1) catalyzing dephosphorylation of the C-terminal domain (CTD) of Pol II subunit POLR2A/RPB1 and SUPT5H/SPT5, (2) degrading the exiting nascent RNA transcript via endonuclease activity and (3) promoting the release of Pol II from bound DNA. The integrator complex is also involved in terminating the synthesis of non-coding Pol II transcripts, such as enhancer RNAs (eRNAs), small nuclear RNAs (snRNAs), telomerase RNAs and long non-coding RNAs (lncRNAs). Within the integrator complex, INTS13 is part of the integrator tail module and acts as a platform for the recruitment of transcription factors at promoters. At prophase, mediates recruitment of cytoplasmic dynein to the nuclear envelope, a step important for proper centrosome-nucleus coupling. At G2/M phase, may be required for proper spindle formation and execution of cytokinesis.
Synonyms: ASUN; C12orf11; GCT1; FLJ10637; NET48; Mat89Bb; SPATA30
Tractability: PROTAC: UniProt records ubiquitination sites on it; ubiquitination databases record sites on it.
Gene: Protein-coding gene on chromosome 12 (26,904,250 to 26,938,331, reverse strand). Ensembl gene ENSG00000064102.
Subcellular location: Nucleus; Cytoplasm
Subcellular location (Human Protein Atlas): Nucleoplasm; Nuclear bodies; Vesicles
Pathways (Reactome):
Gene expression (Transcription): RNA polymerase II transcribes snRNA genes
Gene Ontology:
Molecular function: DNA-binding transcription factor binding; protein binding
Biological process: centrosome localization; mitotic spindle organization; protein localization to nuclear envelope; regulation of mitotic cell cycle; regulation of transcription elongation by RNA polymerase II; RNA polymerase II transcription initiation surveillance; snRNA processing; flagellated sperm motility; regulation of fertilization
Cellular component: cytoplasm; INTAC complex; integrator complex; nuclear body; nucleoplasm; nucleus
Genetic constraint (gnomAD): Loss-of-function variants: 23 observed, 71.05 expected, observed/expected ratio (o/e) 0.32, 90% interval 0.23 to 0.46. The upper end of that interval is the gene's LOEUF score, 0.46, which puts it in group 2 of 6, group 1 being the genes least tolerant of losing a copy. Missense variants: 483 observed, 733.09 expected, observed/expected ratio (o/e) 0.66, 90% interval 0.61 to 0.71. Synonymous variants: 250 observed, 241.42 expected, observed/expected ratio (o/e) 1.04, 90% interval 0.93 to 1.15.
Homologues: Orthologues: chimpanzee INTS13 (100% identical), macaque INTS13 (99% identical), pig INTS13 (99% identical), rabbit INTS13 (99% identical), dog INTS13 (98% identical), mouse Ints13 (96% identical), rat Ints13 (96% identical), guinea pig INTS13 (92% identical), tropical clawed frog ints13 (86% identical), zebrafish ints13 (79% identical), Drosophila melanogaster asun (37% identical), Caenorhabditis elegans ints-13 (27% identical).
Diseases named in the same sentence as INTS13 in open-access papers:
INTS13 is named in the same sentence as 24 diseases in open-access papers, as found by Europe PMC text mining. Sharing a sentence is not in itself a finding about the gene and the disease. The quoted sentences say what the papers report.
cervical cancer (2 papers, 2015 to 2025). A primary or metastatic malignant neoplasm involving the cervix. "In this study, our primary goal was to comprehensively investigate the functional role and underlying mechanisms of INTS13 in cervical cancer." (PMID 41429980, 2025). "These consistent findings across multiple cervical cancer cell types underscore the pervasive role of INTS13 in promoting the malignant phenotypes associated with cervical cancer." (PMID 41429980, 2025). "This increased binding between ZNF384 and the INTS13 promoter region appears to be a crucial mechanism underlying the observed overexpression of INTS13 in cervical cancer tissues." (PMID 41429980, 2025). "This rigorous approach ultimately led to the selection of INTS13 as a novel and clinically relevant target for detailed study in cervical cancer." (PMID 41429980, 2025). "Here, we comprehensively investigated the role of integrator complex subunit 13 (INTS13) in cervical cancer progression." (PMID 41429980, 2025). "The expression of INTS13 was found to be significantly elevated within cervical cancer tissues when compared to adjacent cervical tissues." (PMID 41429980, 2025). "These collective and compelling findings establish hnRNPC as an indispensable downstream mediator through which INTS13 exerts its pro-cancerous effects within cervical cancer cells." (PMID 41429980, 2025). "The in vivo animal studies demonstrated that targeted silencing of INTS13 effectively inhibited pCCa-1 cervical cancer xenograft growth in nude mice." (PMID 41429980, 2025). "Here, we found that INTS13-promoted cervical cancer growth is mediated through its effect on hnRNPC expression." (PMID 41429980, 2025). "The consistent manifestation of these inhibitory effects across diverse cervical cancer cell types emphatically underscores the indispensable role of INTS13 in fostering the malignant phenotypic characteristics of cervical cancer cells." (PMID 41429980, 2025). "To comprehensively delineate the functional ramifications of INTS13 inhibition, we investigated its impact on the induction of apoptosis within cervical cancer cells." (PMID 41429980, 2025). "Quantitative densitometric analysis of the Western blot data of all twenty pairs of tissues further confirmed a significant elevation in INTS13 protein expression within human cervical cancer tissues compared to paracancerous cervical tissues." (PMID 41429980, 2025). "To further substantiate the pivotal role of INTS13 in the progression of cervical cancer, we employed CRISPR/Cas9 gene editing technology to generate INTS13 knockout (koINTS13) primary pCCa-1 cervical cancer cell lines." (PMID 41429980, 2025). "To further elucidate the pro-oncogenic role of INTS13, we engineered primary pCCa-1 cervical cancer cells to stably overexpress INTS13 utilizing a lentiviral construct." (PMID 41429980, 2025). "Our investigation elucidated an upstream regulatory mechanism for INTS13 overexpression in cervical cancer." (PMID 41429980, 2025). "These robust correlations and functional validations strongly support the notion that INTS13 plays a pro-oncogenic role in cervical cancer." (PMID 41429980, 2025). "Consistently, both mRNA and protein levels of INTS13 were found to be significantly elevated in all three primary cervical cancer cell types, in stark contrast to the low expression observed in priCEpi-1 (respectively)." (PMID 41429980, 2025). "These in vivo findings collectively support that INTS13 actively promotes cervical cancer growth in vivo, fostering tumor growth and concurrently inhibiting apoptosis." (PMID 41429980, 2025). "Therefore, the TCGA-based analysis shows that INTS13 is overexpressed in cervical cancer, correlates with tumor T-stage, exhibits high diagnostic potential, and serves as an independent prognostic marker for poorer OS in cervical cancer patients, particularly those with higher body weight." (PMID 41429980, 2025).
cervical cancer (continued). "In vitro functional studies demonstrated that genetic silencing or CRISPR/Cas9-mediated knockout of INTS13 significantly inhibited the proliferation, migration, and invasion of primary cervical cancer cells, while selectively inducing apoptosis." (PMID 41429980, 2025). "We identified hnRNPC as a critical downstream effector, demonstrating that INTS13 regulates its expression in pCCa-1 primary cervical cancer cells." (PMID 41429980, 2025). "Subsequent OS analyses, based on TCGA cervical cancer data, revealed that the expression level of INTS13 significantly impacted the prognosis of cervical cancer patients." (PMID 41429980, 2025). "To validate the expression profile of INTS13 in cervical cancer, we next comprehensively assessed INTS13 mRNA and protein levels across human cervical tissues and derived cell types." (PMID 41429980, 2025). "The consistent overexpression of INTS13 in cervical cancer tissues, its correlation with advanced disease and poorer survival, and its functional validation in vitro and in vivo underscore its potential as a valuable therapeutic target." (PMID 41429980, 2025). "A statistically significant upregulation of INTS13 mRNA expression was observed in surgically-treated human cervical cancer tissues (“T” ) when compared to adjacent paracancerous cervical tissues (“N”) (n = 20)." (PMID 41429980, 2025). "Next, our investigation was expanded to encompass other primary cervical cancer cell types (pCCa-2, pCCa-3) and the established HeLa cell line, utilizing the same lentiviral INTS13 overexpression construct." (PMID 41429980, 2025). "Our results provided compelling evidence that INTS13 represents a promising therapeutic target for cervical cancer." (PMID 41429980, 2025). "To ascertain the functional significance of INTS13 to cervical cancer progression, we utilize shRNAs for the targeted suppression of INTS13 expression in primary pCCa-1 SCC cervical cancer cells." (PMID 41429980, 2025). "Our analysis of TCGA datasets revealed a consistent overexpression of INTS13 across various histological subtypes of cervical cancer, which significantly correlated with advanced tumor T-stage and predicted poorer OS, particularly in patients with higher body mass index." (PMID 41429980, 2025). "Moreover, the migratory ability of these cervical cancer cells was significantly enhanced upon INTS13 overexpression." (PMID 41429980, 2025). "Collectively, these findings unequivocally demonstrate a significant increase in INTS13 expression in cervical cancer tissues from surgically-treated patients and in primary cervical cancer cells, while exhibiting low expression in paracancerous tissues and primary human cervical epithelial cells." (PMID 41429980, 2025). "To broaden the generalizability of these findings, we extended our investigation to examine the apoptotic effects of INTS13 silencing (specifically employing shINTS13-Sq3) in additional primary cervical cancer cell types (pCCa-2, pCCa-3) and the established HeLa cervical cancer cell line." (PMID 41429980, 2025). "In vitro functional studies corroborated these findings, demonstrating that genetic silencing or CRISPR/Cas9-mediated knockout of INTS13 markedly inhibited the proliferation, migration, and invasion of primary cervical cancer cells while selectively inducing apoptosis." (PMID 41429980, 2025). "Our analysis of publicly available The Cancer Genome Atlas (TCGA) datasets revealed that INTS13 is significantly overexpressed in cervical cancer tissues across various histological subtypes, correlating with advanced tumor T-stage and predicting poorer overall survival." (PMID 41429980, 2025). "Furthermore, our investigation extended to INTS13 expression in primary human cervical epithelial cells (priCEpi-1 ) and primary cervical cancer cells isolated from three individual patients (namely pCCa-1, pCCa-2, pCCa-3, also reported previously)." (PMID 41429980, 2025).
cervical cancer (continued). "Conversely, the ectopic overexpression of INTS13 (oeINTS13-Slc1) in pCCa-1 cells resulted in a marked elevation in both hnRNPC mRNA and protein levels, thereby confirming that INTS13 positively regulates hnRNPC expression in pCCa-1 cervical cancer cells." (PMID 41429980, 2025). "Mechanistically, we identified heterogeneous nuclear ribonucleoprotein C (hnRNPC) as a critical downstream effector, with INTS13 regulating hnRNPC expression, and the restoration of hnRNPC effectively reversing the anti-cervical cancer effects observed upon INTS13 silencing." (PMID 41429980, 2025). "Our study collectively establishes INTS13 as a crucial precancerous gene in cervical cancer." (PMID 41429980, 2025). "To precisely delineate the cellular localization and functional associations of INTS13 at a single-cell resolution, we conducted an in-depth analysis of scRNA sequencing data derived from cervical SCC samples, as SCC accounts for 80–90% of all cervical cancer cases." (PMID 41429980, 2025). "Finally, in vivo animal models confirmed that targeted silencing of INTS13 significantly impeded cervical cancer xenograft growth in nude mice, reduced cellular proliferation, and augmented apoptosis, consistently accompanied by a reduction in hnRNPC expression." (PMID 41429980, 2025). "To experimentally validate the predicted regulatory interplay between ZNF384 and INTS13, we precisely modulated ZNF384 expression in cervical cancer cells." (PMID 41429980, 2025). "However, in stark contrast to the observations in cervical cancer cells, INTS13 silencing in priCEpi-1 and priCEpi-2 cells failed to induce apoptosis, as evidenced by unchanged TUNEL staining and the absence of a statistically significant increase in cell death." (PMID 41429980, 2025).
cholangiocarcinoma (2 papers, 2017 to 2025). A carcinoma that arises from the intrahepatic biliary tree (intrahepatic cholangiocarcinoma) or from the junction, or adjacent to the junction, of the right and left hepatic ducts (hilar cholangiocarcinoma). "Notably, INTS13, which is significantly up-regulated in rectum adenocarcinoma, lung cancer small cells, and cholangiocarcinoma, is the most frequently deregulated INT gene at the transcriptional level (eight out of 22 analyzed cancer types)." (PMID 28468258, 2017).
ovarian tumors (2 papers, 2013 to 2017). "Additionally, the INTS13 gene was confirmed as being significantly overexpressed in kidney and ovarian tumors." (PMID 28468258, 2017).
breast carcinoma (1 paper, 2017). "Additionally, INTS7 is specifically over-expressed in breast cancer, whereas INTS8 and INTS13 is particularly over-expressed in kidney renal clear cell carcinoma." (PMID 28468258, 2017).
ciliopathy (1 paper, 2022). A genetic disorder of the cellular cilia or the cilia anchoring structures, the basal bodies, or of ciliary function. "Altogether, we show that mutations in INTS13 cause an autosomal recessive ciliopathy, which reveals key interactions between components of the Integrator complex." (PMID 36229431, 2022). "Our results also provide evidence that INTS13 is a novel ciliopathy gene, and phenotypes associated with INTS13 mutation are likely due to a dysfunction in Integrator-mediated transcriptional regulation." (PMID 36229431, 2022).
colon cancers (1 paper, 2017). "However, statistically significant differences in the expression of INTS7, INTS8, and INTS13 between tumor and healthy samples were only measured for breast and colon cancers." (PMID 28468258, 2017).
thyroid cancer (1 paper, 2017). "Although not significant, a mild reduction of INTS7, INTS8, and INTS13 expression was measured in thyroid cancer samples compared to normal ones." (PMID 28468258, 2017).
tumor (5 papers, 2013 to 2025). "Furthermore, scRNA sequencing pinpointed INTS13 expression predominantly within malignant epithelial cells of the tumor microenvironment, where its expression was associated with genes involved in critical cellular processes such as RNA processing and mitochondrial functions." (PMID 41429980, 2025). "Single-cell RNA sequencing further localized INTS13 expression predominantly to malignant epithelial cells within the tumor microenvironment, where its expression correlated with genes involved in critical cellular processes." (PMID 41429980, 2025). "Upon surgical excision of the designated tumor tissues (one xenograft per group of each group, at Day-24 and Day-36), we proceeded to analyze the expression profiles of INTS13 and hnRNPC, alongside key markers indicative of cellular proliferation and apoptosis." (PMID 41429980, 2025). "The re-analysis of TCGA RNA-Seq data from paired samples (tumor vs. healthy) revealed a robust over-expression of INTS7, INTS8, and INTS13 genes in different tumors." (PMID 28468258, 2017). "A transcriptome analysis of paired (normal and tumor) samples revealed that the transcription of INTS7, INTS8, and INTS13 is significantly altered in several cancers." (PMID 28468258, 2017).
cancer (4 papers, 2017 to 2025). A tumor composed of atypical neoplastic, often pleomorphic cells that invade other tissues. "Few studies have focused on the expression, functional role and mechanism of action of INTS13 in human cancer." (PMID 41429980, 2025). "To experimentally validate this observed correlative relationship, we investigated the impact of INTS13 modulation on hnRNPC expression within primary pCCa-1 cancer cells." (PMID 41429980, 2025). "Crucially, the restoration of hnRNPC expression effectively reversed the anti-cancer effects observed upon INTS13 silencing, highlighting hnRNPC as a key mediator in the INTS13-driven oncogenic pathway." (PMID 41429980, 2025). "Remarkably, despite not being able to definitely establish INTS7 and INTS8 as cancer driver genes, the transcriptome analysis of RNA-Seq paired samples revealed that these two genes, together with INTS13, are the most deregulated across cancers." (PMID 28468258, 2017). "INTS9, INTS11, INTS13, and INTS14 were mutated in very few cancer types, with a very low mutation rate." (PMID 28468258, 2017). "We also detected an interaction between the Drosophila C7orf26 ortholog and fly Integrator and observed co-essentiality between C7orf26 and INTS10, INTS13, and INTS14 in the Cancer Dependency Map (Data S2)." (PMID 35688146, 2022).
neurodevelopmental disorder (2 papers, 2023). A behavioral and cognitive disorder with onset during the developmental period that involves impaired or aberrant development of intellectual, motor, or social functions. "As a result, we identified a dozen candidate genes: TSPAN11 as a potential KS candidate gene, TM7SF3, STK38L, ARNTL2, ERGIC2, TMTC1, DENND5B, and ETFBKMT as candidate genes for the neurodevelopmental disorder, and INTS13, REP15, PPFIBP1, and FAR2 as candidate genes for KS with ID." (PMID 37563198, 2023). "The results identified one potential KS candidate gene (TSPAN11), seven candidate genes for the neurodevelopmental disorder (TM7SF3, STK38L, ARNTL2, ERGIC2, TMTC1, DENND5B, and ETFBKMT), and four candidate genes for KS with ID (INTS13, REP15, PPFIBP1, and FAR2)." (PMID 37034680, 2023).
INTS13 also shares sentences with these, for which no sentence is quoted: cervical squamous cell carcinoma (1 paper); developmental delays (1); germ cell tumor (1); granulosa cell tumor (1); hepatocellular carcinoma (1); intellectual disabilities (1); lung adenocarcinoma (1); lung carcinoma (1); microcephaly (1); ovarian granulosa cell tumor (1); rectum adenocarcinoma (1); seminoma (1); small cell lung carcinoma (1); testicular seminoma (1).